CNNM4 (cyclin and CBS domain divalent metal cation transport mediator 4)
Description:
Probable metal transporter. The interaction with the metal ion chaperone COX11 suggests that it may play a role in sensory neuron functions (By similarity). May play a role in biomineralization and retinal function.
Synonyms: ACDP4; KIAA1592; SLC70A4
Tractability: Antibody: UniProt places it where antibodies can reach, with high confidence; UniProt predicts a signal peptide or a membrane-spanning region; its Gene Ontology location is reachable by antibodies, with medium confidence. PROTAC: ubiquitination databases record sites on it; its protein half-life has been measured.
Gene: Protein-coding gene on chromosome 2 (96,760,898 to 96,811,888, forward strand). Ensembl gene ENSG00000158158.
Subcellular location: Cell membrane
Subcellular location (Human Protein Atlas): Actin filaments; Plasma membrane
Gene Ontology:
Molecular function: protein binding; magnesium ion transmembrane transporter activity; sodium ion transmembrane transporter activity
Biological process: intracellular monoatomic cation homeostasis; magnesium ion homeostasis; magnesium ion transport; magnesium ion transmembrane transport; sodium ion transmembrane transport
Cellular component: plasma membrane; protein-containing complex; basolateral plasma membrane
Genetic constraint (gnomAD): Loss-of-function variants: 32 observed, 54.16 expected, observed/expected ratio (o/e) 0.59, 90% interval 0.44 to 0.79. The upper end of that interval is the gene's LOEUF score, 0.79, which puts it in group 3 of 6, group 1 being the genes least tolerant of losing a copy. Missense variants: 784 observed, 1,046.4 expected, observed/expected ratio (o/e) 0.75, 90% interval 0.71 to 0.8. Synonymous variants: 410 observed, 454.15 expected, observed/expected ratio (o/e) 0.9, 90% interval 0.83 to 0.98.
Gene-disease validity (ClinGen):
ClinGen rates the evidence that CNNM4 causes each of these diseases.
Jalili syndrome (autosomal recessive): Definitive. Jalili syndrome is characterized by the association of amelogenesis imperfecta (AI) and cone-rod retinal dystrophy (CORD).
Homologues: Orthologues: chimpanzee CNNM4 (99% identical), rabbit CNNM4 (94% identical), dog CNNM4 (92% identical), pig CNNM4 (92% identical), rat Cnnm4 (90% identical), mouse Cnnm4 (89% identical), guinea pig CNNM4 (87% identical), macaque CNNM4 (81% identical), zebrafish cnnm4b (67% identical), tropical clawed frog cnnm4 (63% identical), Drosophila melanogaster uex (42% identical), zebrafish cnnm4a (40% identical), and 5 more. Paralogues in human: CNNM2 (63% identical), CNNM1 (47% identical), CNNM3 (39% identical).